EGFR (epidermal growth factor receptor)
Diseases named in the same sentence as EGFR in open-access papers (continued):
Sharing a sentence is not in itself a finding about the gene and the disease.
cancer (continued). "Further, to determinate the effect of these mAbs on EGFR and its downstream signaling pathway, we have selected two cetuximab-resistant cancer cells (GEO-CR and SW48-CR) and their parental cell lines." (PMID 28978055, 2017). "Having demonstrated that miR-200c increased radiosensitivity in cancer cells with activated EGFR signaling, we next planned to confirm the mechanism of radiosensitization." (PMID 29029445, 2017). "TACE also plays an essential physiological role in growth factor signaling, by shedding multiple activating ligands of the epidermal growth factor receptor (EGFR), a receptor important for epithelial development, homeostasis, and cancer." (PMID 29045841, 2017). "Supralethal PDT also downregulated various proteins involved in EGFR signaling, which is an important therapeutic target as it is overexpressed in numerous cancer types." (PMID 27803950, 2017). "As previously shown, the combination of two antibodies targeting non overlapping epitopes on EGFR act synergistic and superior to individual antibodies in terms of target elimination and cancer cell growth inhibition." (PMID 28978055, 2017). "In accordance, CMP can significantly inhibit the levels of ki-67 and EGFR signaling in cancer tissues." (PMID 29212184, 2017). "Anti-EGFR CAR-T therapy is an alternative strategy for EGFR overexpression malignant cancers, although the application of CAR-T therapy toward solid tumors remains challenging." (PMID 28356156, 2017). "Epithelial-mesenchymal transition is of critical importance for the generation of cancer stem cells and EGFR inhibitors block EMT at the invasive front of ESCCs." (PMID 28930282, 2017). "In breast stem-like cancer cells, strong PLA signals were observed for GD3/EGFR association, whereas less obvious PLA signals were observed for GD2/c-Met association." (PMID 28537895, 2017). "This justifies further preclinical development of 55Co-labelled Affibody molecules for PET-imaging of EGFR expression in malignant tumours." (PMID 28729680, 2017). "The phase II MyPathway trial evaluated agents targeting the HER2, BRAF, Hedgehog, or EGFR pathways in patients with advanced cancer." (PMID 29285234, 2017). "EGFR triggers AKT-centered oncogenic signaling pathways, and high EGFR levels also signify a high state of cancer cellular respiration." (PMID 29211022, 2017). "In a previous experimental study it has been shown that MM151 is potentially more effective than first generation anti-EGFR mAbs in inhibiting EGFR signaling and cancer cell growth, and in inducing EGFR down-regulation." (PMID 29137301, 2017). "Infact, protein lysates from harvested resistant tumors showed higher vimentin levels and EGFR-inhibitors resistant cancer cells established in vitro showed high invasive and migrative abilities." (PMID 28416737, 2017). "Human epidermal growth factor receptor 3 (HER3) is important in maintaining epidermal growth factor receptor-driven cancers and mediating resistance to targeted therapy." (PMID 28899363, 2017). "Epidermal Growth Factor Receptor (EGFR) antagonists were one of the first anti-cancer treatments developed targeting a Receptor Tyrosine Kinase." (PMID 28970798, 2017). "Anti-EGFR-GN with a desired NIR wavelength (approximately 808 nm) is an ideal contrast agent for application of both cancer cell imaging and NIR-PTT." (PMID 29156817, 2017). "Here, we report that EGFR regulates the IBC cell population that expresses cancer stem-like cell (CSC) markers through COX-2, a key mediator of inflammation whose expression correlates with worse outcome in IBC." (PMID 28978083, 2017). "Given the prominent importance of EGFR signaling in cancer development, scientists have developed the following strategies: anti-EGFR monoclonal antibodies and small-molecule EGFR tyrosine kinase inhibitors (TKIs)." (PMID 28218686, 2017). "The current study clearly demonstrates that CAFs consist of subpopulations that can differ in their effects on cancer cell sensitivity to EGFR-TKIs." (PMID 28429795, 2017).
cancer (continued). "We discuss the potential utility of a combination of inhibitors of SFK, FAK, or both to overcome the resistance of cancer cells to multiple EGFR-TKIs." (PMID 29050315, 2017). "Next, binding properties to native EGFR on the surface of cancer cells was investigated via flow cytometry." (PMID 29137329, 2017). "Our work establishes a physiological context in which iRhom phosphorylation occurs, placing it within the settings of infection (activation of Toll-like receptors by bacteria and viruses) and cancer (EGFR transactivation by G protein-coupled receptors)." (PMID 29045841, 2017). "The in vivo antitumour efficiency of Anti-EGFR-CIL-miR-135a was assessed in GBC-SD cancer-bearing mice." (PMID 28729631, 2017). "FGFR is also involved in autocrine activation of STAT3 as a positive feedback in many previously treated cancer cells that are driven by oncogenes such as EGFR, ALK, MET, and KRAS." (PMID 28030802, 2017). "We report bispecific PEG engagers that simultaneously bind to PEG on nanomedicines and EGFR on cancer cells for selective delivery of PEGylated stealth nanocarriers to EGFR+ TNBC cells." (PMID 28593948, 2017). "Several signalling pathways that play key roles in cancer, e.g. EGFR pathway, FGF pathway, spliceosome, proteasome, FcγR mediated signalling, were also found to be enriched in the selected genes." (PMID 28481952, 2017). "No cells with EGFR overexpression were observed in tumors treated with triplet therapy, while many cancer cells with EGFR overexpression were found in the other groups." (PMID 28388009, 2017). "Based on current knowledge, EGFR or HER2 is the main driver of downstream signaling in cancers that are highly sensitive to EGFR or HER2 inhibitors, primarily via the MAPK and the phosphatidylinositol 3-kinase (PI3K)/AKT pathways." (PMID 29237412, 2017). "EGFR signaling (belonging to tyrosine kinase signaling) is involved in growth signaling, differentiation, adhesion, migration and survival of cancer cells." (PMID 28754127, 2017). "ADAM substrates include many cancer-related proteins, such as Notch receptors and their ligands, epidermal growth factor receptor (EGFR) ligands, interleukin-6 receptor (IL-6R), tumor necrosis factor (TNF) and its receptors, E-cadherin, and CD44." (PMID 28148288, 2017). "We then applied this tutorial to additional cancer types and immunohistochemistry markers – bladder/ki67, lung/EGFR, and oesophageal/CD8 – to establish accuracy compared with experts." (PMID 27959886, 2017). "The EGFR-related signaling is crucial for the development of tumors and is a therapeutic target for treatment of cancers." (PMID 29152147, 2017). "Epidermal growth factor receptor (EGFR) overexpression is related to the increased aggressiveness, metastases, and poor prognosis in various cancers." (PMID 28445134, 2017). "In cancer treatment, overexpression of EGFR pathway proteins and P-glycoprotein 1 confers resistance to a variety of structurally and functionally diverse anticancer drugs." (PMID 28801576, 2017). "A variety of EGFR-targeting chemotherapeutic drugs, such as tyrosine kinase inhibitors (TKIs), and monoclonal antibodies (mAbs) have been developed to treat cancer patients by blocking EGFR signal transduction." (PMID 28031526, 2017). "These names were chosen for simplicity and based on the known role of AKT signaling in cancer cell survival and the known role of EGFR/RAS signaling in cellular growth." (PMID 28446242, 2017). "The DMAs containing affibody (peptide ligand with high affinity for EGFR) (aff+) were effectively internalized by EGFR-expressing cancer (A431) cells, while the endocytic uptake of affibody-free DMAs by A431 cells was negligible." (PMID 29229979, 2017). "Like ALK, second and third generation inhibitors are being developed for several targets, notably EGFR and mTOR, which can extend treatment options for kinase-driven cancers as they progress." (PMID 28431544, 2017).
cancer (continued). "In the present study, we demonstrate that 2D and 3D cancer models exhibit different drug sensitivities towards both targeted inhibitors of EGFR signaling and broad acting cytotoxic agents." (PMID 29296175, 2017). "Owing to overexpressing of some proteins, for example epidermal growth factor receptor (EGFR), in cancer cells with drug resistance, specific monoclonal antibody-modified nanoparticles can be used to overcome EGFR resistance cancer." (PMID 29191057, 2017). "For the first time, an AIEgen-conjugated monoclonal antibody is designed for “turn-on” and “wash-free” imaging of EGFR-overexpressed cancer cells." (PMID 30155197, 2017). "The Epidermal Growth Factor Receptor (EGFR) is a transmembrane tyrosine kinase in 7p11.2, It is one of the critical oncogenes for several cancers and variably expressed from embryogenesis to adulthood in the normal brain development." (PMID 28938685, 2017). "Recently, it was demonstrated that NRP2 regulates mTOR signaling, β-catenin signaling, endosome maturation, and EGFR trafficking sustaining cancer development." (PMID 28804523, 2017). "Due to the fact that many tumors of epidermal origin express high levels of this cell surface receptor, antagonists targeting the EGFR were also amongst the first biologicals approved for the treatment of cancer patients." (PMID 28970798, 2017). "In this review, we discuss the roles of EGFR in cancer development, therapeutic strategies for targeting EGFR, and resistance mechanisms to EGFR-targeted therapies, with a focus on cancer therapies for individual patients." (PMID 29140271, 2017). "A recent interesting study revealed that FGFR-TACC3 fusion protein can promote the resistance of EGFR-dependent cancer cell lines to EGFR/ErbB3 blockage via activation of ERK signaling." (PMID 27956147, 2017). "She underwent a lobectomy, but the cancer recurred; in spite of palliative therapy (conventional chemotherapy, EGFR targeted therapy, and radiotherapy), her cancer progressed slowly for 5 years." (PMID 29123093, 2017). "This RIT is designed by taking advantage of the unique specificity of mAb806 to the EGFR and EGFRvIII overexpressed in cancer." (PMID 28752098, 2017). "High levels of nuclear EGFR have been found in various types of cancers, and nuclear EGFR signaling has been reported to mediate radio-resistance and chemo-resistance, such as to ionizing radiation and cisplatin." (PMID 28513565, 2017). "As one of essential signaling cascades characterized well in stem cell differentiation and proliferation, Sonic Hedgehog (SHH) pathway interacts with other cancer-associated signaling molecules like RAS/RAF/MEK/ERK, PI3K/AKT/mTOR, EGFR, and Notch9." (PMID 28507311, 2017). "Over-expression of cyclin D1 and EGFR proto-oncogenes has been reported in different types of cancer, and in more recent studies EGFR inhibitors have been used for cancer treatment." (PMID 29354245, 2017). "We used a second FLCN-deficient cancer cell line, FTC-133 cells, to examine EGFR signalling following amino acid and growth factor starvation and stimulation with EGF ligand." (PMID 28656962, 2017). "Another protein involved in survival and conferring drug resistance in cancer is the epidermal growth factor receptor (EGFR), often found aberrantly (over)expressed in carcinomas." (PMID 28887666, 2017). "To investigate the expression level of the EGFR in cancer cells, we performed Western blotting analysis of candidate cancer cells." (PMID 28887524, 2017). "Cordycepin, an active component in CMP, can inhibit cancer cell proliferation, mitosis, and EGFR signaling, and increase cell apoptosis." (PMID 29212184, 2017). "We found that either pathway independently protected sensitive cancer models against anti-EGFR antibody treatment in vitro and in vivo." (PMID 28507280, 2017). "The EGFR’s link to cancer was first recognized when the transforming v-ErbB oncogene of the avian erythroblatosis virus was found to be a mutant homolog of human EGFR." (PMID 28513565, 2017).
cancer (continued). "EGFR and its downstream signaling pathways are closely related to cell proliferation, cancer progression, metastasis and angiogenesis." (PMID 29108234, 2017). "Our recent study demonstrated that EGFR-modulated autophagy under hypoxia plays a dual role in cell survival and cell death in the same cancer cell line." (PMID 28338617, 2017). "c-Met signaling is mainly responsible for cancer cell survival when EGFR inhibitors, such as gefitinib, are used during cancer treatment." (PMID 28086832, 2017). "In turn, EMMPRIN and CD44 can phosphorylate Tyr1068 EGFR, establishing a regulatory loop that fosters cancer cell proliferation and invasion." (PMID 28465354, 2017). "EGFR has been identified as a key driver of proliferation and survival signaling in malignant tumors; therefore, we sought to investigate RPN2 silencing-mediated OST impact on EGFR function." (PMID 29069815, 2017). "Rak has inhibitory effects on cell proliferation and epidermal growth factor receptor (EGFR) signaling in a variety of cancer cells." (PMID 29156836, 2017). "This has led to investigating how EGFR can contribute to cell survival and how cancer cells can overcome inhibition of its signaling." (PMID 28338617, 2017). "The inhibition of EGFR in various cancers with EGFR inhibitors, including monoclonal antibodies or tyrosine kinase inhibitors, lead to G1/S arrest." (PMID 28513565, 2017). "Consistent with this notion is our data showing that EGFR was activated by MUC1 in PTX-resistant cancer cells and more importantly, MUC1 inhibition resulted in diminished activity of EGFR and reduced expression of ABCB1 leading to reversal of PTX resistance." (PMID 28796259, 2017). "Dysregulation of the epidermal growth factor receptor (EGFR) promotes cancer cell growth, invasion and metastasis." (PMID 28703807, 2017). "The roles of EGFR and ErbB2 in cancer development are presently well established, whereas data on ErbB3 and ErbB4 are still rather fragmentary." (PMID 28417948, 2017). "Our results improve our understanding of the involvement of EGFR signaling in cancer, toward the goal of helping prevent cancer-related mutagenesis and drug resistance." (PMID 28276478, 2017). "Both, HER2 and EGFR are therefore interesting targets to therapeutically address systemic disease that have already proven beneficial for cancer patients." (PMID 27683128, 2017). "This is of interest because aside from gatekeeper mutations, there is also evidence that FGFR inhibitor resistance can come from a switch to ERBB2/3 signaling (structurally related to EGFR) in models of FGFR3-dependent cancer cell lines." (PMID 28030802, 2017). "Drugs targeting a signaling network, such as EGFR signaling pathway, often become ineffective as acquired resistance develops in cancer cells." (PMID 28288164, 2017). "The rotation of the transmembrane domains for the regulation of EGFR activity is also able to explain the inside-out transmembrane signaling, and presents new opportunities for the design of anti-cancer drugs." (PMID 28574446, 2017). "We conclude that PEG engagerEGFR can increase the anticancer activity of PEGylated medicines (Doxisome and PEG-liposomal vinorelbine) to EGFR+ cancer cells." (PMID 28593948, 2017). "Cancer cells overexpress growth factor receptors, such as the epidermal growth factor receptor (EGFR) and glucose transporters giving them advantages towards proliferation and survival." (PMID 29125563, 2017). "AC480 is a highly selective and potent small-molecule inhibitor of EGFR/HER kinase family, and inhibit cancer cell proliferation through targeting EGFR and HER2 kinases." (PMID 29190914, 2017). "GE11-Ori-Se NPs were found to induce cancer cell apoptosis by inducting ROS production, activating mitochondria-dependent pathway, inhibiting EGFR-mediated PI3K/AKT and inhibiting Ras/Raf/MEK/ERK pathways." (PMID 29019267, 2017).
cancer (continued). "Ge, a small-molecule TKI against EGFR, inhibits cancer growth mainly through targets the adenosine triphosphate binding sites in the cytoplasmic domain of EGFR." (PMID 28531218, 2017). "The investigation was performed in high- (SMMC-7721) and low- (MCF-7) EGFR-expressing cancer cell models." (PMID 29271876, 2017). "Due to large homology of human and canine EGFR, dogs suffering from spontaneous EGFR+ cancer can be considered as ideal translational models." (PMID 29137329, 2017). "Targeting EGFR, CL4 impairs integrin αvβ3-EGFR complex on cancer cells, causing inhibition of integrin binding to matrix and, in turn, VM." (PMID 28425453, 2017). "Tyrosine kinase inhibitors (TKIs) that act against the epithelial growth factor receptor (EGFR) were once widely used in chemotherapy for many human cancers." (PMID 28978341, 2017). "The present work is focused on the activation of LysRS by Epidermal Growth Factor Receptor (EGFR), as increased EGFR activity has been associated with various types of cancers." (PMID 29029422, 2017). "In accordance, CMP treatment can significantly decrease the levels of ki-67 and EGFR signaling molecules in cancer tissues." (PMID 29212184, 2017). "Excessive activation of EGFR and of the downstream signal transducers are found in many diverse cancers." (PMID 29018350, 2017). "The cetuximab-conjugated AIEgen shows red fluorescence only when it is internalized and accumulated in cancer cells with overexpressed epidermal growth factor receptor through endocytosis." (PMID 30155197, 2017). "Taken together, these findings suggest that RanBP6 serves as EGFR regulator that is disrupted in human cancer." (PMID 29229958, 2017). "Gene expression of EMT and cancer stem cell (CSC) markers as well as protein level of EGFR signaling molecules were analyzed by qPCR and western blotting, respectively." (PMID 28468237, 2017). "First, we demonstrated that Akt inhibitors interacted synergistically with Microtubule-Targeting Agents (MTAs) and specifically in cancer cell lines, including those resistant to chemotherapy agents and anti-EGFR targeted therapies." (PMID 28332584, 2017). "The powerful capacity of each of the multitude of pathways under the EGFR’s control to drive cell proliferation and resist apoptosis has formed a strong motivation for their cancer-related researches." (PMID 28513565, 2017). "Our finding supports a model in which sortilin sorts EGFR, modulating its accumulation at the cell surface, and thereby prevents autocrine and sustained signaling, both of which are hallmarks of cancer." (PMID 29084952, 2017). "The more active EGFR signaling in distal CRC meant that left-sided cancers benefited significantly more from cetuximab." (PMID 29085005, 2017). "Understanding these interactions of growth factor signaling (EGFR) and stress responses (autophagy) will provide more effective therapeutic strategies to the cancer characteristics and hence the patient." (PMID 28338617, 2017). "There are several clinically available EGFR or Erbb2 inhibiting cancer therapies, with low or minimal known cardiotoxicity." (PMID 28924210, 2017). "Epidermal growth factor receptor (EGFR), a well-known oncogenic driver, contributes to the initiation and progression of a wide range of cancer types." (PMID 28724430, 2017). "In normal cells, the expression of EGFR is estimated to be from 40,000–100,000 receptors per cell, whereas overexpression of more than 106 receptors per cell is observed in cancer cells." (PMID 28513565, 2017). "As shown for anti-EGFR IgA2 antibodies before, the generated IgA2 antibodies directed against EGFR or Her2 inhibit the proliferation of cancer cell lines." (PMID 28952521, 2017). "In this study, we constructed a third-generation CAR against wild-type EGFR-positive cancers and sought to investigate synergistic therapeutic efficacy of the CAR-modified NK-92 cells combined with cabozantinib in a mouse model of human RCC." (PMID 29423418, 2017).